GPX3 (glutathione peroxidase 3)
Diseases named in the same sentence as GPX3 in open-access papers (continued):
Sharing a sentence is not in itself a finding about the gene and the disease.
Hypertension (5 papers, 2013 to 2025). The presence of chronic increased pressure in the systemic arterial system. "The combination of the GPX3 rs3828599 TC/CC genotype, alcohol use, and advanced age defines a high-risk hypertension subgroup with increased oxidative stress." (PMID 41152890, 2025). "This study investigated the associations among the GPX3 rs3828599 polymorphism, serum GPx-3 levels, and hypertension risk in a high-morbidity rural Chinese cohort and explored relevant interactions between lifestyle and metabolic factors." (PMID 41152890, 2025). "Previous research has shown that in the general Thai population, the GPX3 rs3828599 polymorphism is independently associated with the incidence of hypertension, elevated triglyceride (TG) levels, and low high-density lipoprotein cholesterol (HDL-C) levels." (PMID 41152890, 2025). "This case‒control study provides robust evidence that the rs3828599 C allele is associated both with reduced circulating GPx-3 levels and with an increased risk of hypertension in a Chinese Han population." (PMID 41152890, 2025). "This research comprehensively elucidates the intricate synergistic interplay among GPX3 rs3828599-related genetic susceptibility, redox imbalance, and environmental risk factors in the pathogenesis of hypertension." (PMID 41152890, 2025). "Our study revealed that heterogeneity in hypertension risk is exemplified by the GPX3 rs3828599 polymorphism." (PMID 41152890, 2025). "Research has indicated an association between GPX3 gene polymorphisms, specifically rs3828599, and hypertension in a rural Han Chinese cohort." (PMID 38927092, 2024). "The GPX3 rs3828599 C allele significantly elevates the risk of hypertension by reducing the activity of GPx-3 and is involved in crucial gene–environment interactions, especially in relation to alcohol consumption and advanced age, resulting in a 4.7-fold increase in the risk." (PMID 41152890, 2025). "In Thai populations, the GPX3 rs3828599-GG variant was linked to the incidence of hypertension." (PMID 38927092, 2024). "An association analysis of 161 SNPS of 10 candidate genes, including GPX3, in a Japanese population with hypertension revealed that no polymorphisms correlated significantly with blood pressure level." (PMID 41152890, 2025). "Downregulation of miR-338-3p could lead to upregulation of GPX3, suggesting its potential as a novel therapeutic target for managing hypertension and vascular damage in CKD patients." (PMID 38927092, 2024).
ischemic stroke (5 papers, 2012 to 2023). A stroke disorder caused by obstruction of blood flow to the brain, due to thrombotic (local blood clot formation) or embolic (due to a blood clot or other material traveling from another site) event. "Using qPCR, we successfully validated several key genes regarding CD11c-associated molecules (Itgax, Gpnmb, Gpx3, Csf1, Spp1, Igf1) in the sham group, Day 7, Day 14, and Day 30 after ischemic stroke." (PMID 36828819, 2023). "The under-expression of GPX3 has been associated with vascular diseases and an increased incidence of ischemic stroke." (PMID 36014793, 2022). "Taken together, these findings indicate that GPx-3 could be a potential new diagnostic biomarker for ischemic stroke." (PMID 32466277, 2020). "GPx-3 is elevated under oxidative stress and is reportedly increased in ischemic stroke patients." (PMID 32466277, 2020).
metabolic syndrome (5 papers, 2019 to 2022). A cluster of metabolic risk factors for CARDIOVASCULAR DISEASES and TYPE 2 DIABETES MELLITUS. "For instance, serum levels of GPx3 are higher in subjects of a Mexican population with metabolic syndrome and cardiovascular risk associated with rs8177409 single-nucleotide polymorphism." (PMID 35205224, 2022). "We further demonstrated that high GRS derived from combined SOD2, SOD3, GPX3, and GSTT1 polymorphisms have a strong association with such atherogenic dyslipidemia." (PMID 31396447, 2019).
non-small cell lung carcinoma (5 papers, 2020 to 2023). A group of at least three distinct histological types of lung cancer, including non-small cell squamous cell carcinoma, adenocarcinoma, and large cell carcinoma. "For non-small-cell lung cancer, microRNA-196a manipulates the expression of GPx3 to inhibit the self-renewal ability of stem cells." (PMID 37484915, 2023). "GPX3 is targeted and downregulated by miR-196a which is overexpressed in non-small-cell lung carcinoma (NSCLC) cancers, leading to attenuation of tumorigenicity and cancer cell growth through upregulation of GPX3." (PMID 34199590, 2021).
stomach adenocarcinoma (5 papers, 2014 to 2025). "In stomach adenocarcinoma, GPX3-driven oxidative stress mediates alterations in pyrimidine metabolism through the AMPK/mTOR signaling pathway." (PMID 41440040, 2025). "Reactivation of GPX3 in gastric adenocarcinoma cell line AGS inhibits cell motility as assessed by wound healing assay." (PMID 24790704, 2014). "In stomach adenocarcinoma cells, GPx3 inhibited the level of pyrimidine metabolism via the ROS/AMPK/mTOR signaling pathway, which could affect the migration and invasive ability of these cancer cells and provide ways to reduce their drug resistance." (PMID 39125992, 2024). "Considering both OS and DFS, high expression of DIO1 and GPX3 indicated improved prognosis in Brain Lower Grade Glioma (LGG) and Stomach adenocarcinoma (STAD)." (PMID 32316597, 2020).
carotid atherosclerosis (4 papers, 2020 to 2024). A thickening and loss of elasticity of the walls of carotid arteries that occur with formation of atherosclerotic plaques. "Further large‐sample prospective studies are needed to confirm the causal relationship and evaluate the underlying mechanism between serum GPx3 and carotid atherosclerosis." (PMID 32862561, 2020). "In conclusion, our study suggested that decreasing serum GPx3 activity is associated with the severity of carotid atherosclerosis in T2DM patients." (PMID 32862561, 2020). "Firstly, the observational design makes it difficult to establish a causal relationship between GPx3 and carotid atherosclerosis." (PMID 32862561, 2020). "Although the underlying mechanism of the regulation of GPx3 activity and its physiological and pathophysiological roles in carotid atherosclerosis remains limited, several speculations may explain this association." (PMID 32862561, 2020). "This study aimed to investigate the relationship between GPx3 activity and carotid atherosclerosis among patients with T2DM." (PMID 32862561, 2020). "The increasing incidence of CVDs has already been documented in diabetic patients, in which lower GPx3 activity might act as an independent predictor for carotid atherosclerosis." (PMID 36553589, 2022). "This study demonstrated that serum GPx3 activity was inversely associated with mean CIMT and carotid plaque, suggesting that lower GPx3 activity may be an independent predictor for carotid atherosclerosis in T2DM." (PMID 32862561, 2020). "However, little is known about the role of GPx3 in carotid atherosclerosis." (PMID 32862561, 2020). "Furthermore, these associations remained significant even after adjusting for potential confounders, indicating that decreased GPx3 activity may play a crucial role in carotid atherosclerosis." (PMID 32862561, 2020). "Our present study indicates that the reduced GPx3 activity was involved in the deterioration of mean CIMT and the presence of carotid plaque, in support of the linking between GPx3 activity and the pathogenesis of carotid atherosclerosis in T2DM subjects." (PMID 32862561, 2020). "However, the relationship between GPx3 activity and carotid atherosclerosis has not been well established." (PMID 32862561, 2020).
endometrial cancer (4 papers, 2020 to 2025). Primary or metastatic malignant neoplasm involving the endometrium (mucous membrane that lines the endometrial cavity). "The ratio of SOD1/GPx3 significantly decreased along with the growing prevalence of the endometriosis (P = 0.0048; 0.324 ± 0.110) and endometrial cancer (P = 0.0003; 0.123 ± 0.027) compared with the healthy controls (1.154 ± 0.336)." (PMID 37968795, 2024). "High expression of GPX3 indicated good prognosis in Pancreatic Adenocarcinoma (PAAD), as well as higher risk in Rectum Adenocarcinoma (READ) and Uterine Corpus Endometrial Carcinoma (UCEC)." (PMID 32316597, 2020).
glioblastoma (4 papers, 2014 to 2021). The most malignant astrocytic tumor (WHO grade IV). "Besides the down-regulation of GPx3 within tumor tissues, the circulating GPx3 was also found to be much lower in the patients with glioblastoma than non-patients which implies that it may possess the prognostic value for cancer patients." (PMID 25333265, 2014).
lung fibrosis (4 papers, 2016 to 2024). "In summary, our in vitro results suggest, that TGF-β and oxidative stress contribute to increased GPX3 expression in lung fibrosis in a cell-type-specific manner, upregulating GPX3 in bronchial epithelial cells and interstitial fibroblasts, respectively." (PMID 27435875, 2016). "We analysed Gpx3 levels and Gpx activity in the time course of bleomycin-induced lung fibrosis and studied tissue distribution in normal and fibrotic mouse lungs." (PMID 27435875, 2016). "This is further underlined by the detection of GPX3 in ELF following lung injury, both in the mouse model of bleomycin-induced lung fibrosis and in ILD, in particular in HP and sarcoidosis." (PMID 27435875, 2016). "Our data highlight that GPX3 is expressed and secreted by mouse and human bronchial epithelial cells already under physiological conditions and increased in mouse and human lung fibrosis." (PMID 27435875, 2016). "Upon development of lung fibrosis following tracheal instillation of bleomycin, Gpx3 expression was observed in many more cells including bronchial epithelial cells and interstitial fibroblasts (right-hand panels)." (PMID 27435875, 2016). "GPx3 upregulation can be also found in non-cancerous fibrotic lung tissues, such as those with idiopathic pulmonary fibrosis, a disease associated with oxidative stress." (PMID 33255360, 2020). "Here, we extracted abundance and detergent solubility of extracellular antioxidant enzymes from a proteomic dataset of bleomycin-induced lung fibrosis in mice and assessed regulation and distribution of glutathione peroxidase 3 (GPX3) in murine and human lung fibrosis." (PMID 27435875, 2016). "Importantly, we show, to our knowledge for the first time, that in bleomycin-induced lung fibrosis, HP, and IPF, GPX3 additionally localizes to the interstitial matrix in lung fibrosis." (PMID 27435875, 2016). "All of these, except for Prdx6, were highly abundant in BALF of control mice under basal conditions (left-hand panel) and Gpx3 and Sod3 were additionally upregulated in BALF during bleomycin-induced lung fibrosis." (PMID 27435875, 2016). "Superoxide dismutase 3 (Sod3), Gpx3, and Gpx activity were increased in mouse BALF during bleomycin-induced lung fibrosis." (PMID 27435875, 2016). "In the present study, we show that levels of the antioxidant protein GPX3 are increased in BALF and tissue during bleomycin-induced lung fibrosis, as well as in BALF of some HP and sarcoidosis patients and in total lung homogenates of IPF patients." (PMID 27435875, 2016). "Using this model we found that Gpx3 was expressed by bronchial epithelial cells, secreted in active form into the ELF, and upregulated in lung fibrosis both in BALF and in lung tissue." (PMID 27435875, 2016). "According to the results of qRT-PCR, the expression levels of ENPP3, PDE7B, and ENTPD1 were elevated, while the expression levels of PNMT, GPX3, and POLR3H were decreased in the lung tissues of bleomycin-induced pulmonary fibrosis mice compared with the sham group." (PMID 36923791, 2023). "Our findings further indicate that TGF-β and oxidative stress, but not TNF-α, contribute to upregulation of GPX3 in lung fibrosis in a cell-type-specific manner." (PMID 27435875, 2016). "Levels of Gpx3 as well as Gpx activity in BALF were highest in the inflammatory phase (day 7) of bleomycin-induced lung fibrosis, suggesting upregulation by inflammatory rather than profibrotic mediators." (PMID 27435875, 2016).
lung squamous cell carcinoma (4 papers, 2020 to 2025). "However, in other tumor tissues GPx3 expression is elevated, and high expression is associated with poor patient outcomes in cancers such as stomach and lung squamous cell carcinomas." (PMID 32781581, 2020). "We confirmed that in several cancer types, including lung squamous cell carcinoma (LUSC), PRAD, KIRP, LUAD, BRCA, and COAD, the expression of GPX3 was significantly lower in tumor tissues." (PMID 36845676, 2023). "CAT, ENO1, NQO1, P4HB, and PDIA6 were unique to LUAD, while CAV1, GAPDH, GPX2, GPX3, and PDIA4 exhibited consistent trends in differential expression in both LUAD and lung squamous cell cancer, significant prognostic survival prediction (p<0.05), and excellent classification effectiveness." (PMID 37955007, 2023).
multiple myeloma (4 papers, 2014 to 2020). "GPX3 hypermethylation correlates with disease poor prognosis and resistance to chemotherapy in head and neck cancer patients and multiple myeloma." (PMID 24790704, 2014). "Hypermethylation of GPX3 in multiple myeloma (MM) may be involved in drug response and interaction with the BM microenvironment." (PMID 33369453, 2020). "In fact, GPX3 promoter hypermethylation is linked to downregulation of GPX3 expression in different types of cancer cells and treatment with 5-Aza to human esophageal adenocarcinoma cancer cells SKGT4 and human myeloma cells KMS11 restores GPX3 gene expression." (PMID 24790704, 2014).
thrombotic disorder (4 papers, 2011 to 2024). "GPX3 is essential for maintaining vascular redox homeostasis, and its deficiency has been linked to thrombotic disorders and familial stroke." (PMID 38927092, 2024). "Regarding this, some studies link increased levels of GPx-3 with vascular complications, and a deficiency or a reduction in GPx-3 are related to an increase in the predisposition to developing a thrombotic disorder." (PMID 25923078, 2015). "Mutation(s) or polymorphism(s) in the plasma GPx-3 gene promoter may predispose to a thrombotic disorder, and constitute a genetic risk factor for thrombotic cerebrovascular disease." (PMID 23675242, 2011).
cardiac hypertrophy (3 papers, 2021 to 2025). "The authors posit that aberrant methylation of the GPX3 promoter impairs the efficacy of GPX3, leading to cardiomyocyte damage owing to incomplete removal of oxygen produced by cardiac hypertrophy, DCM, and myocarditis associated with heart failure." (PMID 40290189, 2025). "First, in accordance with the observed CM size increase, higher expressed DEGs were associated with cardiac hypertrophy (e.g., Nppa, Gpx3, Sparc)." (PMID 39304345, 2024). "Cardiac hypertrophy in response to triiodothyronine or isoproterenol treatment was found to upregulate the expression of MsrB1, GPX3, GPx4, and Txnrd1, leading to the speculation that their increased expression may mitigate cardiac damage following induction of hypertrophy." (PMID 34579115, 2021).
chronic obstructive pulmonary disease (3 papers, 2020 to 2026). A chronic and progressive lung disorder characterized by the loss of elasticity of the bronchial tree and the air sacs, destruction of the air sacs wall, thickening of the bronchial wall, and mucous accumulation in the bronchial tree. "GPx3 expression is decreased in patients with smoking-induced chronic obstructive pulmonary disease due to the chronic adaptations." (PMID 33255360, 2020). "GPx3 expression is decreased in the lungs of cigarette smoke-induced chronic obstructive pulmonary disease (COPD) patients." (PMID 32781581, 2020).
diabetic kidney disease (3 papers, 2019 to 2026). Progressive kidney disorder caused by vascular damage to the glomerular capillaries, in patients with diabetes mellitus. "Neutralization of ROS by this enzyme is related to decreased glucose-dependent kidney and vascular damage, which suggests that GPx3 exerts an crucial role against oxidative stress and it may act as a potential therapeutic target for diabetic kidney disease." (PMID 39282151, 2022). "Our data indicated that miR-320a aggravated renal disfunction in DN by targeting MafB and downregulating Nephrin and Gpx3 in podocytes, which suggested that miR-320a could be a potential therapeutic target of diabetic nephropathy." (PMID 31102503, 2019). "The presence of oxidative stress in DM_CKD tissue was further supported by our observation of decreased GPX3 levels as well as increased lipid peroxidation in LV tissue, which is consistent with data from mice models of CKD and GPX1 levels in patients with diabetic kidney disease." (PMID 41419687, 2026).
endometriosis (3 papers, 2020 to 2024). The growth of functional endometrial tissue in anatomic sites outside the uterine body. "Interestingly, endometriosis-associated gene dysregulation in early secretory phase matches dysregulation in the transgenic mouse endometrium in the present study in terms of affected gene-set, above all the progesterone-regulated genes (e.g. Errfi1, Bcl6, Cited2, Irs2, Tgfb2, Gpx3, Tk1)." (PMID 38346980, 2024).
endothelial dysfunction (3 papers, 2020 to 2021). In vascular diseases, endothelial dysfunction is a systemic pathological state of the endothelium (the inner lining of blood vessels) and can be broadly defined as an imbalance between vasodilating and vasoconstricting substances produced by (or acting on) the endothelium. "As in the GPx3-deficient mice, Txnrd2ECKO mice also had endothelial dysfunction, confirming a role for NO insufficiency in promoting a prothrombotic environment and indicating that GPx3 and endothelial Txnrd2 are important regulators of bioavailable NO and thrombosis." (PMID 34579115, 2021). "Furthermore, deficiency of GPx3 decreased circulating cGMP and caused endothelial dysfunction, consistent with a lack of bioavailable NO." (PMID 34579115, 2021). "In patients with nonsevere endothelial dysfunction, a first cluster of proteins (apolipoprotein F and E, glutathione peroxidase 3 [GPx3], and fibrinogen β chain) was up-regulated and down-regulated after the low-fat diet and the Mediterranean diet, respectively." (PMID 32903262, 2020).
head and neck cancer (3 papers, 2017 to 2021). A primary or metastatic malignant neoplasm affecting the head and neck. "Our previous study found that promoter of GPX3 gene was hypermethylated in head and neck cancer, and GPX3 hypermethylation is associated with cisplatin-based chemoresistance and a poor prognosis in head and neck cancer." (PMID 31032363, 2019).
heart failure (3 papers, 2017 to 2025). Inability of the heart to pump blood at an adequate rate to meet tissue metabolic requirements. "Further study will be necessary to reveal the physiological significance of electrophilic modification of Gpx3 during the development of heart failure." (PMID 28790356, 2017). "Focusing on the redox status in the blood of mice with heart failure, we demonstrated that oxidative modification of plasma Gpx3 protein was well correlated with the severity of maladaptive cardiac remodeling induced by pressure overload." (PMID 28790356, 2017). "As the inhibition of TRPC3, but not TRPC6, actually suppressed pressure overload-induced heart failure, oxidative modification of Gpx3 will be a novel biomarker for diagnosing the severity of maladaptive cardiac remodeling." (PMID 28790356, 2017).